MACC1 (MET transcriptional regulator MACC1)
Diseases named in the same sentence as MACC1 in open-access papers (continued):
Sharing a sentence is not in itself a finding about the gene and the disease.
Cirrhosis (2 papers, 2013 to 2020). A chronic disorder of the liver in which liver tissue becomes scarred and is partially replaced by regenerative nodules and fibrotic tissue resulting in loss of liver function. "Cryoablation is a safe and effective therapeutic option for patients with advanced HCC and Child-pugh class A or B cirrhosis; and a higher intratumoral expression of MACC1 or nuclear translocation predicts poor outcomes of cryotherapy in these patients." (PMID 23414367, 2013). "Our data extended the previous findings and suggested that intratumoral MACC1 mRNA expression might serve as a clinical surrogate for clinical presentation and post cryoablation outcomes in patients with HBV-related cirrhosis and BCLC stage C HCC." (PMID 23414367, 2013).
colon adenoma (2 papers, 2016 to 2021). An adenoma that arises from the colon. "We report a significant MACC1 protein expression induction in colon adenoma patients’ tissue and a significant induction of circulating MACC1 transcripts in colon adenoma patients’ blood, compared to lesion-free volunteers." (PMID 27439755, 2016). "In the future, the multimarker combinations of circulating MACC1 transcripts with further blood-based mRNA markers as well as with blood-based miRNA markers might be beneficial for the improvement of diagnosis and prognosis of colon adenoma patients." (PMID 27439755, 2016).
colorectal adenocarcinoma (2 papers, 2015 to 2023). The most common type of colorectal carcinoma. "Within colorectal adenocarcinomas, a significant increase of MACC1 from tumor center to front (p = 0.0012) was detected." (PMID 25884643, 2015). "Here, we investigate the geographic expression pattern of MACC1 in colorectal adenocarcinoma and tumor buds in correlation with clinicopathological and molecular features for improvement of survival prognosis." (PMID 25884643, 2015).
deafness (2 papers, 2023 to 2024). An inherited or acquired condition characterized by the complete loss of the ability to hear from one or both ears. "First suggestions in this regard arise from the findings of an association between MACC1, Schwannoma and deafness, the emerging context of MACC1 and cancer-associated depression (affecting the catecholamine pathway) as well as a correlation of MACC1 and pulmonary arterial hypertension." (PMID 39580452, 2024). "The data presented here are a rationale for further investigation of a presumable role of MACC1 in sporadic VS pathogenesis, especially VS cell invasion and concomitant deafness of patients." (PMID 37627117, 2023). "MACC1 mRNA expression was significantly correlated with deafness in sporadic VS patients (p = 0.034)." (PMID 37627117, 2023). "Indeed, MACC1 expression was 1.7-fold higher in the subgroup of patients with sporadic VS suffering from deafness at least once pre-operatively, compared to patients who never suffered from deafness (p = 0.034)." (PMID 37627117, 2023). "Therefore, it was analyzed whether MACC1 mRNA expression might be related with deafness in sporadic VS patients during their clinical course before initial surgery." (PMID 37627117, 2023).
hilar cholangiocarcinoma (2 papers, 2019 to 2024). A cholangiocarcinoma that arises from the junction, or adjacent to the junction, of the right and left hepatic ducts. "Interestingly, an elevated MACC1 expression was detected in patients with a history of tumor recurrence in another study focusing on intrahepatic and hilar cholangiocarcinoma patients, confirming that MACC1 can be used as an independent prognostic biomarker for the OS of Klatskin tumor patients." (PMID 39580452, 2024).
inflammatory bowel disease (2 papers, 2022 to 2024). A spectrum of small and large bowel inflammatory diseases of unknown etiology. "In CRC associated with inflammatory bowel diseases (IBD), stimulation of the tumor necrosis factor (TNF) receptor 1 by TNF-α led to a NF-κB activation and c-Jun-dependent transcriptional upregulation of MACC1." (PMID 39580452, 2024).
lentivirus infection (2 papers, 2022 to 2024). Virus diseases caused by the Lentivirus genus. "After overexpressing MACC1 in PANC-1 cells via lentivirus infection, cells had a stronger ability to metastasize to the liver." (PMID 36333284, 2022).
liver cirrhosis (2 papers, 2011 to 2020). "Perhaps the expression of MACC1 SNP rs4721888 may provide an explanation to these phenomenon, and may serve as marker in early stage of liver cirrhosis and to predict the prognosis of vascular invasive HCC." (PMID 32047570, 2020). "Compared with this result, our study have found that the MACC1 rs4721888 is associated with higher risk of vascular invasion in HCC patients among drinkers, and most of the HCC patients involved in our study have liver cirrhosis (82.3%) and classified as Child-Pugh grade A (79.9%)." (PMID 32047570, 2020).
malignant glioma (2 papers, 2015 to 2017). A grade III or grade IV glioma arising from the central nervous system. "In addition, a MACC1-specific shRNA was designed and synthesized in order to investigate the effects of MACC1 inhibition on malignant glioma U251 cells." (PMID 26043756, 2015). "Therefore, the U251 cell line was selected to investigate the effects of MACC1 silencing on the proliferation and metastasis of malignant glioma cells." (PMID 26043756, 2015). "Thus suggesting that MACC1 is a key regulator of these upstream signaling pathways, and may be a potential therapeutic target for malignant gliomas." (PMID 26043756, 2015). "The inhibition of MACC1 expression suppressed the activity of MMP-2 as well as MMP-9, leading to a decreased capacity for invasion and metastasis in malignant glioma cells." (PMID 26043756, 2015).
metastatic cancer (2 papers, 2021 to 2024). A carcinoma which has spread from the original site of growth to another anatomic site. "MACC1 was overexpressed in primary and metastatic cancer colon and was associated with poor prognosis." (PMID 34577857, 2021). "All of these endeavors certainly require clinical trials, but we have to face these challenges to successfully fight metastatic cancer—here at the level of MACC1-induced metastasis as a new therapeutic paradigm." (PMID 39580452, 2024). "MACC1 is considered as a main regulator of tumorigenesis and cancer metastasis in primary and metastatic cancer of the colon." (PMID 34577857, 2021).
metastatic melanoma (2 papers, 2023 to 2024). A melanoma that has spread from its primary site to another anatomic site. "On the other hand, seven (78%) of nine metastatic melanomas show intermediate to high expression of both MACC1 and MET." (PMID 37496665, 2023). "However, this correlation appears stronger in metastatic melanomas, where seven (78%) of nine cases show intermediate to high expression of both MACC1 and MET." (PMID 37496665, 2023). "We also found coexpression of relatively high levels of MACC1 and MET in the majority of metastatic melanoma cases." (PMID 37496665, 2023). "Therefore, we evaluated if there is a correlation between MACC1 and MET expression in benign nevi, primary and metastatic melanomas." (PMID 37496665, 2023). "When we performed this analysis, we found no significant quantitatively linear correlation between MACC1 and MET expression levels in nevi (R2 = 0.062), primary (R2 = 0.02), and metastatic melanomas (R2 = 0.14)." (PMID 37496665, 2023).
Obesity (2 papers, 2024). Accumulation of substantial excess body fat. "Although also linked to metabolism but independent from cancer formation, a relationship between MACC1 and obesity has been described." (PMID 38611008, 2024). "Additionally, rats with high-fat diet-induced obesity demonstrated higher MACC1 levels and a more severe colon tumor outcome." (PMID 38611008, 2024). "For instance, the issue of the normal physiological role of MACC1 in tissue and blood of healthy individuals where MACC1 is hardly detectable in most of these samples, its involvement in stemness, in developmental processes, or its role in the context of obesity." (PMID 39580452, 2024).
oral cancer (2 papers, 2021 to 2023). "In conclusion, MACC1 SNP rs4721888 would elevate the susceptibility for oral cancer, and SNP rs975263 would increase the metastasis risk for oral cancer patients with a betel quid chewing habit." (PMID 34072650, 2021). "We estimated the odds ratios (ORs) to study the association of the five MACC1 independent SNPs with oral cancer incidence by logistic regression models." (PMID 34072650, 2021). "This study is the first research on the effect of MACC1 SNPs with oral cancer, and we also found that people with GC genotype or C-allele in rs4721888 would have a higher risk of oral cancer susceptibility than GG genotype." (PMID 34072650, 2021). "In order to realize the effects of the five genetic variants in MACC1 SNPs on oral cancer patients with betel quid chewing, we analyzed if the MACC1 SNPs had relevance to the patients’ clinicopathological characteristics." (PMID 34072650, 2021). "Patients with a polymorphic C allele of MACC1 rs4721888 tended to have an increased risk of oral cancer among those who had a betel quid chewing habit." (PMID 34072650, 2021). "However, the relationships between MACC1 SNPs (single nucleotide polymorphisms) and oral cancer are still blurred." (PMID 34072650, 2021). "The result proved the synergistic effect of the MACC1 SNPs, and environmental risk factors for oral cancer, and could be further studied to apply the rs4721888 genetic marker for diagnosis and prevention and to develop the rs975263 genetic marker for prognosis." (PMID 34072650, 2021). "Because MACC1 is correlated with cancer metastasis, we also analyzed the relationships between the genotypes in the 5 MACC1 SNPs of oral cancer patients with betel quid chewing habits and their clinicopathological reports." (PMID 34072650, 2021). "Nonetheless, it still needs more studies on the relationship between oral cancer and MACC1." (PMID 34072650, 2021). "Therefore, we conducted studies on five MACC1 SNPs, rs3095007, rs1990172, rs4721888, rs975263, and rs3735615 to investigate their diagnosable benefits of oral cancer patients in aspects of the disease process, the prognosis, and the clinicopathological characteristics in central Taiwan." (PMID 34072650, 2021). "Here, we disclosed the relationship of oral cancer and MACC1 SNPs and found that people with GC genotype or C-allele genotype in rs4721888 would have a higher risk of oral cancer incidence whether the risk factors were adjusted or not." (PMID 34072650, 2021). "There were no obvious correlations between the incidences of oral cancer and MACC1 SNPs when comparing the genotype frequencies of the 5 MACC1 SNPs in the case-control study." (PMID 34072650, 2021). "Nonetheless, the relationships of MACC1 SNPs with clinical variables, clinical outcomes, and the development of oral cancer have not been studied." (PMID 34072650, 2021).
renal pelvis carcinoma (2 papers, 2014 to 2019). A carcinoma arising in the renal pelvis. "As shown in this study, we demonstrated for the first time that an abnormally high level of MACC1 expression is associated with a poor prognosis of renal pelvis carcinoma and is indeed an independent prognostic indicator for disease-free survival and overall survival of patients." (PMID 24949951, 2014). "Currently, we are investigating the possibility of quantification of MACC1 transcripts and proteins in the plasma isolated from patients with renal pelvis carcinoma." (PMID 24949951, 2014). "Multivariate analysis with a Cox proportional-hazards model suggested that MACC1 is indeed an independent prognostic indicator of overall survival and cancer-free survival for patients with renal pelvis carcinoma." (PMID 24949951, 2014). "In our present study, we investigated the role of MACC1 in the development and progression of human renal pelvis carcinoma." (PMID 24949951, 2014). "We have demonstrated in immunohistochemical assays the expression pattern of MACC1 protein in human renal pelvis carcinoma tissue specimens as well as in the normal renal pelvis." (PMID 24949951, 2014). "Surprisingly, in the malignant renal pelvis carcinoma tissues, MACC1 is stained predominantly in the cytoplasma although the expression level of MACC1 is substantially higher than that found in the normal renal pelvis epithelium." (PMID 24949951, 2014). "In this study, we investigated the role of MACC1 in the development and progression of renal pelvis carcinoma, a form of upper tract urothelial carcinomas." (PMID 24949951, 2014). "Finally, we also examined by using univariate and multivariate analyses the eligibility of MACC1 as a novel independent prognostic indicator for renal pelvis carcinoma." (PMID 24949951, 2014). "The correlation between immunohistochemical scores of MACC1 protein expression (indicated as the values of the average optical density (AOD) measured by Image Pro Plus in renal pelvis carcinoma tissue sections) and prognostic factors (gender, age, TNM stage, and nuclear grade)." (PMID 24949951, 2014). "It would certainly be of great interest in the near future to examine whether there is indeed a high level of aberrant genomic DNA amplification and/or rearrangement in the genomic DNA fragment containing the MACC1 locus in patients with renal pelvis carcinoma." (PMID 24949951, 2014). "Multivariate Cox regression analysis of several prognostic factors (TNM stage, nuclear grade, and MACC1 protein expression levels) with respect to five-year overall survival (OS) and disease-free survival (DFS) of patients with renal pelvis carcinoma (RPC)." (PMID 24949951, 2014). "Univariate Cox regression analysis of several prognostic factors (age, gender, TNM stage, nuclear grade, and MACC1 protein expression levels) with respect to five-year overall survival (OS) and disease-free survival (DFS) of patients with renal pelvis carcinoma." (PMID 24949951, 2014). "In addition, we examined the correlation between MACC1 overexpression and clinicopathological parameters (including age, gender, tumor-node-metastasis (TNM) stage and pathological grade), as well as disease-free survival (DFS) and overall survival (OS) in patients with renal pelvis carcinoma." (PMID 24949951, 2014).
sarcoma (2 papers, 2024). A usually aggressive malignant neoplasm of the soft tissue or bone. "Interestingly, MACC1 was able to induce c-MET expression in the U-2OS sarcoma cell line but not in non-cancerous human umbilical vein endothelial cell (HUVEC), indicating that MACC1 requires the presence of c-MET-specific transcription factors." (PMID 39580452, 2024).
benign breast diseases (1 paper, 2016). "Serum MACC1 levels were elevated in BC patients compared with patients with benign breast diseases or healthy volunteers." (PMID 27793048, 2016).
benign breast tumors (1 paper, 2016). "In the current study we retrospectively examined serum MACC1 status in BC patients, patients with benign breast tumors, and healthy volunteers to assess the value of MACC1 as a biomarker." (PMID 27793048, 2016).
brain tumors (1 paper, 2020). "So far, only MACC1-dependent expression of adhesion molecules, but not distribution, was assessed in non-brain tumors." (PMID 32503676, 2020).
cervical adenocarcinoma (1 paper, 2025). An adenocarcinoma arising from the cervical epithelium. "Thirteen genes were found to be differentially expressed in cervical adenocarcinoma samples using microarray databases and literature reports, but only the MACC1, HOXC8, BCL2, and RARβ genes were the most representative of the expressed genes." (PMID 40361484, 2025). "In conclusion, this exploratory pilot study, through its robust and holistic analysis, provides evidence that MACC1, HOXC8, RARβ, BCL2, and E6/E7 could be promising molecular markers for the detection of cervical adenocarcinomas." (PMID 40361484, 2025).
cervical intraepithelial neoplasia (1 paper, 2020). "Genotypic frequencies of 5 MACC1 SNPs rs975263, rs3095007, rs4721888, rs3735615 and rs1990172 were identified for 132 patients with invasive cancer, 99 with high-grade cervical intraepithelial neoplasia and 338 normal controls using real-time polymerase chain reaction." (PMID 32174779, 2020).
colorectal adenoma (1 paper, 2016). An adenoma that arises from the colon or rectum. "Ren and colleagues published a stepwise elevation of MACC1 expression in key points of CRC development (colorectal adenoma, early-stage invasive and advanced adenocarcinoma with liver metastasis) by IHC suggesting that MACC1 may contribute to cancer initiation and early invasive growth." (PMID 27439755, 2016).
COVID-19 (1 paper, 2021). A disease caused by infection with severe acute respiratory syndrome coronavirus 2. "Thus, this MACC1 variant may be interacting with CM health to mediate greater COVID-19 severity." (PMID 35096005, 2021).
Crohn disease (1 paper, 2020). A gastrointestinal disorder characterized by chronic inflammation involving all layers of the intestinal wall, noncaseating granulomas affecting the intestinal wall and regional lymph nodes, and transmural fibrosis. "By contrast, inflamed tissues from ulcerative colitis and Crohn's disease patients revealed moderate to strong MACC1 expression mainly in the cytoplasm of the cells, indicating the association of chronic inflammation and increase in MACC1 expression." (PMID 32670264, 2020). "We have shown that MACC1 expression is increased in inflamed tissue of ulcerative colitis and Crohn's disease patients." (PMID 32670264, 2020). "In order to provide insights of MACC1 gene expression in inflamed tissue before tumor development we stained tissues from ulcerative colitis and Crohn's disease patients for MACC1." (PMID 32670264, 2020).
depression (1 paper, 2024). "This is also linked to the question, if MACC1 might play a role in other, non-cancerous diseases, such as Schwannoma, depression and hypertension." (PMID 39580452, 2024).
endometrioid carcinoma (1 paper, 2018). "MACC1 mRNA high expression was significantly correlated with poor OS in 523 cases with serous carcinoma (HR = 1.48 (95% CI: 1.16 – 1.89), P = 0.0014) and in 30 patients with endometrioid carcinoma (HR = 7.31 (95% CI: 0.76 – 70.29), P = 0.043)." (PMID 30515418, 2018).
esophageal squamous cell carcinoma (1 paper, 2022). Esophageal squamous cell carcinoma (ESCC) is a type of esophageal carcinoma (EC) that can affect any part of the esophagus, but is usually located in the upper or middle third. "In our study, the positive expression rate of MACC1 in esophageal squamous cell carcinoma was 53.5%." (PMID 35242498, 2022). "MACC1, c-Met, and cyclin D1 proteins are closely related to the occurrence and development of esophageal squamous cell carcinoma." (PMID 35242498, 2022). "Our results suggest that MACC1 is a cancer-promoting factor in patients with esophageal squamous cell carcinoma, and its high expression indicates poor prognosis in patients." (PMID 35242498, 2022). "MACC1 and c-Met proteins are closely related to the occurrence and development of esophageal squamous cell carcinoma." (PMID 35242498, 2022). "MACC1 may affect the prognosis of patients with esophageal squamous cell carcinoma by regulating the expression of the c-Met/cyclin D1 axis." (PMID 35242498, 2022). "The purpose of this study was to preliminarily analyze the expressions of MACC1, c-Met, and cyclin D1 in esophageal squamous cell carcinoma and their relationship with clinicopathological parameters, as well as the effects of the expressions of the three proteins on the prognosis of ESCC." (PMID 35242498, 2022). "The purpose of this study was to analyze the expression of MACC1, c-Met, and cyclin D1 in esophageal squamous cell carcinoma and their relationship with clinicopathological parameters and to initially clarify the mechanism of action of the three in esophageal squamous cell carcinoma." (PMID 35242498, 2022).